HIF1A (hypoxia inducible factor 1 subunit alpha)
Diseases named in the same sentence as HIF1A in open-access papers (continued):
Sharing a sentence is not in itself a finding about the gene and the disease.
tumor (continued). "As no real data on the role of hypoxia in pHGGs are published up to date, our first step in this work was to analyze tumor samples of pHGG and DIPG to screen if biomarkers involved in mTOR/ HIF-1α pathway were upregulated." (PMID 29069732, 2017). "In contrast, another study suggests hypoxia-induced autophagy in tumor cells is dependent on AMP-activated protein kinase and mTOR, thus excluding a role for HIF-1α, BNIP3, and BNIP3L." (PMID 28316954, 2017). "Hypoxia, a tumor microenvironment, induces VEGF-A and VEGF-C/−D expression via HIF1α, promoting angiogenesis and lymphangiogenesis respectively." (PMID 28423707, 2017). "In tumor cells, as expected, HIF-1α immunostaining was confined to the nuclei whereas CAIX, MCT1 and MCT4 decorated the tumor cell membranes." (PMID 28099149, 2017). "HIF-1a is a key oxygen-regulator of VEGF gene expression which is important for angiogenesis and thus tumor growth." (PMID 28832662, 2017). "in vivo mice study showed that BA/CDM combination significantly suppressed AML tumor growth, and overexpression of SOD2 and a constitutive HIF1α (HIF1C) completely diminished this effect." (PMID 29212263, 2017). "Strikingly, however, deletion of HIF-1α in NK cells and a reduction in sVEGFR1 levels in VEGF null tumours rescued VEGFR2 signalling and tumour growth along with restored angiogenesis and alleviated hypoxia." (PMID 29150606, 2017). "Hypoxia-/HIF-1α directly or indirectly (in the latter case via ADO, lactate or acidosis) can drive the expression of VEGF and activate VEGF-R, thus promoting tumor evasion from immune surveillance." (PMID 29312351, 2017). "We found that TSP1 production in tumors from CD47-deficient mice was significantly reduced compared to those in WT mice, likely due to markedly reduced HIF-1A, VEGF production and hypoxia-induced tumor necrosis." (PMID 27283989, 2017). "As expected, we also observed tumor‐promoting factors (TGFβ, VEGF, MMP‐2, MMP‐9, and HIF‐1α) were reduced in BDM‐treated groups compared with the control animals." (PMID 28211615, 2017). "Since it has been reported that emetine suppresses the expression of HIF-1α, which is a key regulator of glucose metabolism, we evaluated HIF-1α expression in the tumor cells using western blotting." (PMID 28055963, 2017). "HIF-1α was also shown to enhance function and differentiation of myeloid derived suppressor cells (MDSC) in the tumor microenvironment." (PMID 28892492, 2017). "More recently, a paper demonstrated that the HIF-1a/CCL20/IDO axis plays a crucial role in accelerating cancer metastasis in hepatocellular carcinoma by inducing EMT and an immunosuppressive tumor microenvironment." (PMID 29197379, 2017). "The results of IHC analysis showed that SFN reduced the level of HIF-1α and VEGF in the tumor tissues, which is consistent with the in vitro results." (PMID 28978924, 2017). "We detected the expression of MTA1 and hypoxia-inducible factor-1α (HIF-1α) and microvessel density (MVD) value in liver tumor tissues and tumor periphery before and after TACE treatment." (PMID 28589145, 2017). "Taken together, by reducing the glycolytic enzyme LDH-A, combined treatment of si-HIF-1α and DDP induces apoptosis in PCa cells, leading to increased ROS production, and subsequently inhibiting tumor growth." (PMID 28790395, 2017). "This demonstrates a unique and unexpected role for HIF-1α in NK cells in the regulation of VEGF bioavailability in the tumour microenvironment and the coupling of vascular remodelling and tumour growth." (PMID 29150606, 2017). "To understand the potential mechanism of miR-30e in inhibiting tumor growth, we showed that miR-30e blocked the activation of AKT and ERK1/2 pathways, and the expression of HIF-1α and VEGF via directly targeting IRS1." (PMID 29162879, 2017).
tumor (continued). "We were reminded of an earlier work showing that serine/threonine kinase PKD2 not only regulates HIF-1α, but also interacts with and participates to various functions coordinated by HSP90, including tumor growth and angiogenesis." (PMID 29100402, 2017). "As the major upstream regulator of HIF-1α expression, EGFR/PI3K/AKT/mTOR and MAPK/ERK1/2 pathways were simultaneously suppressed by F2 in U87 cells and xenograft tumor model." (PMID 29156717, 2017). "In CRC they have antagonising roles, with HIF-1α acting oncogenic and HIF-2α acting tumour suppressive." (PMID 28536364, 2017). "Compared to normal livers (control), mRNA and protein levels of HIF-1α and HIF-2α in tumor cells increased in the vehicle group, while the group treated with IDA showed decreased HIF-1α and HIF-2α levels, compared to the vehicle group." (PMID 28423608, 2017). "The expression levels of four genes (HIF1A, MTHFD1, GGH and TYMS) in tumor tissue before CRT can predict the response to preoperative CRT including S-1 or UFT/LV." (PMID 28417167, 2017). "Considering the positive correlation between A2AR and HIF-1α in HNSCC tissues, we suggested that A2AR interfere the tumor progression rate partially depend on hypoxia status." (PMID 28592285, 2017). "In an agreement with human SqCC, KL and xenograft SqCC tumours exhibit significantly increased AKT activity and downstream signalling directing the stabilization of HIF-1α and GLUT1 expression." (PMID 28548087, 2017). "HIF-1α and HIF-2α are the two best-studied isoforms of HIFs, and are now considered important therapy targets for various tumor types." (PMID 28423608, 2017). "Clinical and animal studies have reported increased HIF-1α after TACE in both plasma and tumour samples 13–15." (PMID 28542038, 2017). "HIF-1α directly regulates the expression of VEGF; therefore, the degree of tumor oxygenation and tumor vascularity are generally parallel." (PMID 29262608, 2017). "Three mammalian α subunit isoforms are known, of which HIF-1α and EPAS1/HIF-2α are known to be related to tumor proliferation and progression." (PMID 28060746, 2017). "TC68 cells, overexpressing concomitantly MYC, p-AKT and HIF-1α proteins (the DIPG tumor with the bar), close to the protein profile of SF188 cells, were showing an equivalent sensitivity as SF188 cells." (PMID 29069732, 2017). "Transcript analysis of colorectal liver metastases has identified the HIF-1α target KDM3A, as a biomarker for hypoxic tumour cells and potential prognostic marker and therapeutic target for CRC." (PMID 28536364, 2017). "In the 1970’s, Folkman proposed the concept of targeting the blood vessels in tumors, to starve the tumor of oxygen and nutrients; however, hypoxia increases HIF-1α and its target, VEGF, resulting in increased blood vessels in the tumor." (PMID 27999195, 2017). "Furthermore, we demonstrate that the expression of PDK1, PHD3, and HIF-1α proteins in NB tumor samples can be used in immunohistochemistry to evaluate the hypoxic status of NB tumors, and could, therefore, be successfully used as a relevant tool to stratify high-risk patients." (PMID 29117193, 2017). "Silencing of either HIF1α or HIF2α has been shown to improve the efficacy of doxorubicin in HCC models by inhibiting cell proliferation, tumor angiogenesis and enhancing cell apoptosis." (PMID 28493839, 2017). "Consistent with the findings in vitro, administration of AE-AS greatly reduced the protein expression of HIF-1α, VEGF, and pVEGFR2, as well as tumor angiogenesis reflected by a decrease of CD31 expression." (PMID 28710377, 2017). "Remarkably, this CTC-subset displayed tumor stem-like features, as evidenced by the expression of key stem-like genes including Bmi1, CD44, Oct4, Notch1, Wnt3a, Stat3, and HIF-1α." (PMID 27738343, 2017). "These premises encouraged us to carry out an in-depth analysis of the role of HIF-1α, SDH, and VHL on miR-210 expression by using knockout murine models and analyses of human tumor material." (PMID 28036268, 2017).
tumor (continued). "While CAF signaling pathways, including VEGF and hypoxia inducible factor 1-alpha (HIF-1α) have been extensively studied, the role of mechanics in tumor progression specifically CAF-generated mechanical forces is poorly understood." (PMID 28974764, 2017). "STAT3 abnormal activity accelerates IL-6, HIF1α and VEGF, specifically in the tumor microenvironment." (PMID 27861147, 2017). "The present in vivo results revealed that OL decreased HFD-induced HIF-1α and GLUT-1 levels in tumor tissues." (PMID 28410190, 2017). "Here, we report for the first time the effects of suppressing HIF-1α, an oxygen-sensitive subunit of HIF-1, in PEL tumor cells." (PMID 28922425, 2017). "We therefore used the same tumours that had earlier been examined histologically for the effect of AZD5363 on tumour vessel density, pimonidazole binding and HIF‐1α, to assess the effect of AZD5363 on vascular endothelial cell proliferation." (PMID 29084756, 2017). "Together, these observations would also suggest that a positive feed-back loop between HIF1α, LOXL2-XBP1 and EMT can operate at least in some tumour contexts that deserve further studies." (PMID 28332555, 2017). "Remarkably, enhanced HIF-1α signal and nuclear localization after DFO-treatment was shown in the HPV-positive HNSCC cells compared to the HPV-negative tumor cells." (PMID 29163780, 2017). "Therefore, we hypothesis HIF-1α may be implicated in inflammation, whose overexpression can activates vascular endothelial growth factor (VEGF) and platelet-derived growth factor (PDGF) that facilitate the tumor angiogenesis." (PMID 29268703, 2017). "There are several TFs, such as EGF1, HIF1A, the E2F family and NANOG, that play different regulatory roles in tumor cells, and it is also known that SP1 expression levels are higher in cancer cell lines than in normal cells." (PMID 28531296, 2017). "In order to further examine the apparent anti‐vascular effects of AZD5363 after RT, we sought to determine the effect of AZD5363 on tumour levels of VEGF and HIF‐1α." (PMID 29084756, 2017). "Since HIF1α itself targets a large variety of genes, MPT0B098 interferes with the post-transcriptional expression of many tumor-related genes involved in tumor growth, cell metabolism, cell survival, and other functions." (PMID 27582706, 2016). "Deficit of oxygen availability within tumor microenvironment directly regulates the HIF-1α signal, however, the activation of HIF-1α is not only induced by hypoxia, but also via various kinases cascade, for example, STAT3." (PMID 27806334, 2016). "Hypoxia upregulates the transcription factor, hypoxia-inducing factor (HIF-1α and HIF-2α), which, in turn, modulates a variety of target gene expressions in metabolism, tumor growth, EMT and metastasis, angiogenesis, and stemness." (PMID 26861406, 2016). "The positive correlation between the same hypoxia gene signature and HIF-1α, VEGFA and SLC2A1 suggests that the imaging parameters reveal real functional aspects reflecting the oxygen status in the tumor." (PMID 27634881, 2016). "The expression of the molecules, including TNF‐α, IL‐1β, HIF‐1α, NF‐κB, VEGF, and MMP9 in tumor tissues was analyzed by the methods of immunohistochemistry and western blot." (PMID 27734611, 2016). "We link HIF1α-dependent hypoxia sensing and TNC expression with an aggressive tumour phenotype, and demonstrate that ECM stiffness directly represses miR-203 expression to activate HIF1α-dependent TNC deposition via a positive feedback loop." (PMID 27820599, 2016). "In tumor MDSC, HIF1α was bound directly to a transcriptionally active hypoxia-response element in the miR-210 proximal promoter." (PMID 27458169, 2016). "The adaptation of tumor to hypoxia is predominantly regulated by HIF-1α and HIF-2α; while highly homologous, HIF-1α and HIF-2α have unique tissue distributions and play critical but non-overlapping roles in tumor progression." (PMID 26846782, 2016).
tumor (continued). "As with HEGU treatment, licoricidin treatment decreased the expression of CD45, HIF-1α, COX-2, iNOS, and P-p65NFκB in tumor tissues." (PMID 27314329, 2016). "HIF-2α and HIF-1α are structurally similar; however, HIF-2α is thought to be less important in EC, with detected HIF-2α expression in less than 20% of tumor cells." (PMID 27634881, 2016). "Since VEGF is a target of both HIF-1α and NF-κB, we cannot exclude the contribution of VEGF secretion as a result of sole NF-κB activation or HIF-1α accumulation in other tumor entities." (PMID 26739387, 2016). "In any case, attenuation of HIF-1α expression was able to reduce tumorigenic capabilities of DTC cells, thus underscoring its contribution to tumor formation." (PMID 27105499, 2016). "Both HEGU and licoricidin treatment reduced pulmonary metastasis and the expression of CD45, CD31, HIF-1α, iNOS, COX-2, and VEGF-A in tumor tissues." (PMID 27314329, 2016). "If HIF-1α is a key inducer that contributes to tumor EMT, the function of HIF-1α in VM formation in CRC should be investigated." (PMID 27806701, 2016). "Both HIF-1α and HIF-2α are more highly expressed in ccRCC tumor tissues than in paired adjacent normal tissues." (PMID 27741516, 2016). "Expression of HIF-1α/HIF-2α/iNOS and VEGF were reduced, despite an increased hypoxic tumour fraction." (PMID 26972697, 2016). "Knockdown of HIF-1α or the β2-AR antagonist (ICI 118, 551) obviously restrained tumor growth compared with the NNK group." (PMID 26497365, 2016). "The inclusion of monitoring of the changes in serum HIF-1α and VEGF levels or HIF-1α and VEGF protein expression in tumor tissues after TACE of HCC patients as part of the efficacy evaluation criteria has enhanced the evaluation of HCC treatment." (PMID 26985249, 2016). "Among the many regulators of tumor angiogenesis, hypoxia-inducible factor-1α (HIF-1α) and vascular endothelial growth factor (VEGF) play vital roles in the regulation of tumor angiogenesis of the residual disease after TACE of HCC." (PMID 26985249, 2016). "Upon tumor entry, CD8+ T cells will be subjected to increasingly severe hypoxia once they leave areas close to blood vessels; this will activate HIF-1α." (PMID 26904023, 2016). "Tumor hypoxia, vascular endothelial growth factor (VEGF), proliferation, and microvascular density (MVD) were assessed by immunostaining for HIF-1α and carbonic anhydrase-9 (CA-9), VEGF, Ki67, and cluster of differentiation-31, respectively." (PMID 26937938, 2016). "Both FDGhi and FDOPAlo phenotypes correlated with higher HK2 expression, which is required for oncogenic transformation in vitro and tumor initiation in vivo and is enhanced by MYCN and HIF-1α." (PMID 26959748, 2016). "In support of this, in the majority of tumor specimens from HBV-related HCC patients, increased expression of HIF-1α was observed and the level correlates with the expression of HBx." (PMID 27094811, 2016). "HIF-1α and HIF-2α are key transcription factors in tumor development and only accumulate in hypoxic tumors." (PMID 26842802, 2016). "Misregulation of HIF protein, especially HIF-1α and HIF-2α, is correlation with tumor development and metastasis." (PMID 26842802, 2016). "It is plausible that the initial exposure to adipocyte-supplied lipids triggers HIF-1α stabilization and that consequent activation of HIF-1α signaling leads to further lipid uptake, perpetuating the hypoxic and glycolytic phenotype in tumor cells." (PMID 27588494, 2016). "As a consequence, mPGES-1+/+ tumor cells expressed high levels of VEGF and HIF-1α, induced endothelial cells activation and formed highly vascularized tumors." (PMID 27322147, 2016). "In human pancreatic neuroendocrine BON1 cells, RSUME stimulates hypoxia-inducible factor-1α (HIF-1α) and vascular endothelial growth factor-A (VEGF-A), which are key components of tumor neovascularisation." (PMID 27506944, 2016).
tumor (continued). "Consistent with these tumor-promoting functions, aberrant expression of several key molecules of the KLHL20/PML pathway, such as HIF-1α, Pin1, and PML, has been reported in many types of cancers." (PMID 27042198, 2016). "A remarkable reduction in the protein levels of HIF-1α, Glut1, and CAIX was also observed in immunohistochemical analysis of sections of tumor tissue from mice treated with metformin." (PMID 26621849, 2016). "The activated networks (HIF1A, ESRRA, ESRRG) had many proteins that were increased in tumor tissues that overlapped between the three targets, such as ENO1/ENO2, ALDOA, and LDHA." (PMID 27128972, 2016). "We have shown that miR-210 is significantly associated with all hypoxia-related markers available for analysis; HIF-1α, CA9, Glut-1, tumour necrosis and expression of a 26-gene head and neck signature." (PMID 27441495, 2016). "Currently, there are a few reports of the changes in HIF-1α and VEGF protein expression in tumor tissues after TACE of HCC patients." (PMID 26985249, 2016). "In agreement with this notion, tumor expression of HURP, along with expression of HIF-1α, VEGF (a HIF-1α target), and HSP60 (involved in the regulation of HIF-1α protein stability) were associated with PCa progression." (PMID 27379206, 2016). "Mechanistically, hypoxia-inducible factor (HIF)-1α induces the EMT repressor ZEB2, which directly downregulates ephrinB2 through promoter binding to enhance tumour invasiveness." (PMID 27470974, 2016). "Cultured tumor tissue produced high levels of intact FGF23 and demonstrated increased expression of HIF-1α protein." (PMID 27468359, 2016). "We analyzed the levels of the tumor markers, VEGF, pSmad and HIF1α, by immunofluorescence microscopic method." (PMID 26951793, 2016). "Its target gene, VEGF-A, is mainly regulated by HIF-1a at the transcriptional level, and VEGF-A also plays a critical role in tumor angiogenesis, growth, and metastasis." (PMID 27456341, 2016). "The previous IHC analysis using TMAs showed a positive linear correlation between the expression of 14-3-3ζ and HIF-1α in primary tumor tissues, especially in PVTT(+) tumor tissues, suggesting a potential relationship between the two proteins." (PMID 26910835, 2016). "Both HIF-1α and14-3-3ζ expression were found to be correlated with tumor size (P < 0.05), microscopic vascular invasion (P < 0.05), PVTT (P < 0.05) and advanced tumor stage (P < 0.01)." (PMID 26910835, 2016). "BCL2 BH4 domain also binds to calcineurin, CED-4, HIF-1α, c-Myc, paxillin, Raf-1, Ras and VDAC, promoting tumorigenesis or tumor survival and contributing to both anti-apoptosis and pro-tumorgenesis activities of BCL2." (PMID 27049723, 2016). "Resistance of tumor cells and particularly of cancer stem cells is achieved by overexpression of ABC transporters driven by the HIF1α transcription factor activated by reduced oxygen tension and/or ROS in the tumor microenvironment." (PMID 26798421, 2016). "Hif1aKA/KA mice exhibited enhanced retinal angiogenesis and tumour vascularization via HIF-1α stabilization, indicating the potential involvement of SET7/9 and LSD1 in regulating retinal and tumour angiogenesis." (PMID 26757928, 2016). "It was shown that hypoxia induced HIF-1α and HIF-2α expression, which upregulated CCR7; inhibiting HIF-1α or HIF-2α resulted in decreased CCR7 expression and furthermore in inhibition of tumor cell migration and invasion." (PMID 27018053, 2016). "As a consequence both HIF-1α and HIF-2α play a pivotal role in tumor angiogenesis and tumor growth of OSCC." (PMID 27044404, 2016). "For example, a hypoxic tumor microenvironment can promote the expression of CD73, as hypoxia-inducible factor-1α (HIF-1α) interaction with its binding site (hypoxia response element, HRE) in the CD73 gene promoter promotes CD73 expression." (PMID 27782859, 2016). "Immunohistochemistry was used to detect the expression of HIF-1a and the vascular specific marker CD34, and tumor growth curves were drawn." (PMID 27456341, 2016).